CLOCK (clock circadian regulator)
Diseases named in the same sentence as CLOCK in open-access papers (continued):
Sharing a sentence is not in itself a finding about the gene and the disease.
schizophrenia (11 papers, 2009 to 2025). A major psychotic disorder characterized by abnormalities in the perception or expression of reality. "Similar gene deficiencies are noted in schizophrenia (CLOCK, PER, CRY), anxiety disorder (CRY), and attention deficit hyperactivity disorder (ADHD) (CLOCK)." (PMID 39584972, 2024). "The interaction between HIF-1 α and CLOCK genes and CLOCK gene alterations in schizophrenia patients seem to be among the possible causes of this prevalence." (PMID 35054894, 2022). "Studies focusing on specific genes and their expression have indicated a significant role for the CLOCK gene in the development of schizophrenia and in the circadian rhythm abnormalities observed as side effects of treatment." (PMID 39584972, 2024). "In individuals with first-episode schizophrenia, the mRNA expression of CLOCK, PER2, and CRY1 genes significantly decreases in the early stages, suggesting that the circadian rhythm disturbance may be part of the pathological process of schizophrenia rather than a result of long-term drug treatment." (PMID 40243466, 2025). "Circadian alterations in expression levels of CLOCK, CRY1, and PER2 mRNA were found in schizophrenia." (PMID 29534090, 2018).
acute myeloid leukemia (10 papers, 2017 to 2024). Acute myeloid leukemia (AML) is a group of neoplasms arising from precursor cells committed to the myeloid cell-line differentiation. "A recent finding of targeting BMAL1 and CLOCK for acute myeloid leukemia (AML) therapy indicates further the pro-cancerous option of clock components." (PMID 28108951, 2017). "CLOCK and BMAL1 were necessary for cell proliferation and stemness maintenance in acute myeloid leukemia." (PMID 37524704, 2023). "CLOCK and BMAL1 showed oncogenic potential in acute myeloid leukemia." (PMID 37524704, 2023). "In addition, previous studies have revealed CLOCK and BMAL1 as key regulators for acute myeloid leukemia (AML) by contributing to proliferation and stemness." (PMID 35246220, 2022). "In acute myeloid leukemia (AML), PER2, PER3, and CRY levels are reduced due to reduced expression of CCAAT/enhancer-binding proteins (C/EBPs), while BMAL1, CLOCK, and PER1 levels increase." (PMID 34966277, 2021).
Insulin resistance (10 papers, 2016 to 2024). Increased resistance towards insulin, that is, diminished effectiveness of insulin in reducing blood glucose levels. "CLOCK gene polymorphisms have also been closely associated with insulin resistance." (PMID 39165284, 2024). "A gene-based approach detected a significant association of CpG methylation pattern in PER2 gene with both blood glucose and insulin resistance There is a similar observation for CLOCK and BMAL genes." (PMID 32344535, 2020). "Gene-based approach detected a significant association of CpG methylation pattern in PER2 gene with both blood glucose and insulin resistance There is a similar observation for CLOCK and BMAL genes." (PMID 32344535, 2020). "At the level of q < 0.05, gene-based analysis detected significant associations of DNA methylation in four circadian genes (CLOCK, BMAL1, PER1, and PER2) with insulin resistance, fasting glucose, or HbA1c." (PMID 31031806, 2019). "Moreover, in our previous study in a US white population we specifically reported a gene-diet interaction between the CLOCK-rs4580704 SNP and the contribution of MUFAs in the diet in determining fasting glucose concentrations and insulin resistance (HOMA-IR)." (PMID 26739996, 2016). "Moreover, we detected a gene-diet interaction between the CLOCK-rs4580704 SNP and monounsaturated fatty acids (MUFA) intake in determining fasting glucose and insulin resistance in GOLDN." (PMID 26739996, 2016). "Recently, by using chromatin immunoprecipitation sequencing, researchers have found that CLOCK and BMAL1 could bind to inner-mitochondrial genes related to insulin sensitivity, suggesting that the relationship between circadian rhythm and insulin resistance may be related to mitochondrial dynamics." (PMID 37215098, 2023).
epilepsy (9 papers, 2012 to 2025). A brain disorder characterized by episodes of abnormally increased neuronal discharge resulting in transient episodes of sensory or motor neurological dysfunction, or psychic dysfunction. "CLOCK knockout specifically resulted in reduced dendritic spine formation and paroxysmal depolarization shift, both molecular hallmarks of epilepsy, caused by altered electrical function of neuronal microcircuits composed of excitatory pyramidal cells." (PMID 36635730, 2023). "Although there is yet little evidence that core clock gene variants predispose or cause epilepsy, CLOCK RNA and protein are downregulated in brain tissue resected from patients with TLE." (PMID 32714261, 2020). "No direct association has been established between abnormalities (e.g., mutation) of major CLOCK gene products and epilepsy." (PMID 23189039, 2012). "Alterations in core clock genes (CLOCK, BMAL1, PER, and CRY) were also noted in children with epilepsy, which was linked to seizure frequency and timing." (PMID 39768659, 2024). "First, circadian rhythm genes (BMAL1 and CLOCK), and their transcription factor complex, BMAL1–CLOCK, are known to influence the expression of other genes that are causally involved in epilepsy (for example, PAR DBP, TEF, and HLF)." (PMID 33192961, 2020). "MLL1, a H3K4 methyltransferase, is associates with CLOCK and recruited to promoters of CCGs in a circadian manner, and null mice of SMCX/JARID1c, a H3K4 demethylase, develops epilepsy." (PMID 23189039, 2012). "In addition, CLOCK, an upstream regulator of these TFs, is necessary in cortical excitatory neurons for maintaining normal network activity and leads to epilepsy when conditionally deleted in these neurons." (PMID 36749029, 2023). "However, the CLOCK gene was found to be under-expressed in the brain tissue of tuberous sclerosis and focal cortical dysplasia patients with treatment-resistant epilepsy, and plays an important role in the excitatory and inhibitory neuron excitability threshold." (PMID 40572688, 2025). "Core clock genes such as CLOCK, Bmal1, PER, and CRY regulate circadian rhythms, which influence the timing and occurrence of seizures in many types of epilepsy." (PMID 40182148, 2025). "Mechanistically, rhythmic cycles and steady-state levels of circadian genes such as BMAL1, CLOCK, PER1, REV-ERBα, and RORα were found to be dysregulated in epilepsy." (PMID 36635730, 2023). "Core clock genes including CLOCK, BMAL1, FBXL21, PER1, PER3, CRY1, and NR1D1 do not show evidence of harboring mutations that cause epilepsy in humans." (PMID 32714261, 2020). "In mice, deletion of CLOCK in excitatory pyramidal neurons but not inhibitory interneurons led to a lowered seizure threshold and overt seizures during sleep, with altered electrophysiological properties of neuronal microcircuits similar to epilepsy." (PMID 34830412, 2021).
Hepatic steatosis (9 papers, 2009 to 2024). Steatosis is a term used to denote lipid accumulation within hepatocytes. "In animal studies, mice with core circadian clock genes (e.g., CLOCK) mutations developed hyperlipidemia, hepatic steatosis and cancer." (PMID 37987396, 2023). "In humans, common genetic variations in CLOCK transcription factor are associated with fatty liver disease." (PMID 19338660, 2009). "CLOCK:BMAL1 are pioneering transcription factors for rhythmic genes, and their disfunction (i.e., through genetic or pharmacologic interventions) has been associated with metabolic disorders, including fatty liver disease." (PMID 39060446, 2024). "Thus, neutrophil depletion decreases Bmal1 expression and the circadian locomotor output cycles kaput (CLOCK) and reduces overall JNK activation, decreasing hepatic steatosis." (PMID 38979415, 2024).
Alzheimer disease (8 papers, 2011 to 2022). A progressive, neurodegenerative disease characterized by loss of function and death of nerve cells in several areas of the brain leading to loss of cognitive function such as memory and language. "The minor allele of CLOCK gene polymorphism 3111T/C was associated with higher susceptibility of Alzheimer’s disease only in APOE ε4 carriers." (PMID 32913680, 2020). "In summary, our results demonstrate that elevated CLOCK and BMAL1 induce the dysfunction and cytotoxicity of astrocytes via the impairment of aerobic glycolysis in Alzheimer’s disease." (PMID 33114015, 2020).
lung carcinoma (8 papers, 2018 to 2025). "Of note, tumoral CLOCK expression is positively associated with stress status, serum NE level and poor prognosis in lung cancer patients." (PMID 39054537, 2024). "As such, CLOCK-deficiency or OLZ reverses NE/chronic stress-induced gemcitabine (GEM) resistance in lung cancer." (PMID 39054537, 2024). "To evaluate the clinical relevance of CLOCK in lung cancer patients, we validated the expression of CLOCK and predicted prognosis using The Cancer Genome Atlas (TCGA) database." (PMID 39054537, 2024). "Consistently, targeting the release of NE with OLZ suppressed CLOCK expression to reverse stress-enhanced lung cancer stemness." (PMID 39054537, 2024). "Clinical evidence identified a positive correlation between CLOCK expression and NE level, and CLOCK served as a promising indicator of chronic stress, cancer development and poor prognosis in patients with lung cancer." (PMID 39054537, 2024). "Decreased NE-releasing prevents activation of ADRB2-cAMP-PKA-CREB pathway to inhibit CLOCK transcription, thus reversing lung cancer stem-like traits and chemoresistance under chronic stress." (PMID 39054537, 2024). "Mechanistically, NE activated ADRB2-cAMP-PKA-CREB pathway to promote CLOCK transcription that sustains lung cancer stem-like traits." (PMID 39054537, 2024). "To evaluate the correlations between stress level, serum NE and CLOCK in patients with lung cancer, we performed prospective analysis of 59 lung cancer cases." (PMID 39054537, 2024). "OLZ inhibited stress-induced neuro-activity in mPFC and NE releasing to suppress the activation of ADRB2-cAMP-PKA-CREB pathway, which reduced phosphorylated CREB that transactivates CLOCK to enhance lung cancer stemness." (PMID 39054537, 2024). "Altogether, these findings suggest that CLOCK is a potential biomarker and a therapeutic target for lung cancer patients under chronic stress." (PMID 39054537, 2024). "Previous studies showed that circadian rhythm-related factors such as the ARNTL, CLOCK, RORA, RORB, CRY1, CRY2, and PER3 genes were associated with a higher risk of lung cancer." (PMID 36385012, 2022). "Epigallocatechin-3-gallate (EGCG) is one of those potential compounds studied for its ability to inhibit self-renewing lung cancer stem-like cells through the inhibition of CLOCK in NSCLC cell line A549 and H1299." (PMID 34959290, 2021). "Importantly, lung cancer patients with elevated expression of CLOCK signatures exhibited significantly poor survival rates using Kaplan–Meier Plotter analysis." (PMID 39054537, 2024). "Further, surgically collected 5 pairs of lung cancer tissues displayed higher mRNA and protein levels of ADRB2 and CLOCK and mRNA level of stemness-related factors than their adjacent normal tissues." (PMID 39054537, 2024).
breast tumor (7 papers, 2014 to 2024). "High activity of ALDH correlates with tumor grade, metastasis, and poor prognosis in patient breast tumor; consequently, low expression levels of CLOCK in ALDH-positive 4T1 cells likely promote their malignant properties by regulating ALDH activity." (PMID 33890571, 2021). "Immunohistochemical analysis of human breast tumor samples revealed high expression of CLOCK in ERα-positive breast tumor samples." (PMID 24789043, 2014). "Healthy breast patient tissues showed lower CLOCK expression than breast tumor tissues." (PMID 29780357, 2018). "The data appeared to suggest a correlation between the ERα and CLOCK in ERα-positive breast tumors." (PMID 24789043, 2014). "Given the apparent correlation between ERα and CLOCK expression in the breast-tumor samples analyzed, we next examined whether CLOCK expression could be stimulated by E2." (PMID 24789043, 2014). "In contrast, CLOCK, NPAS2, CIART/CHRONO, BHLHE40, RORA, and RORC were significantly up-regulated in these breast tumors." (PMID 38319971, 2024). "A higher percentage of ERα-positive breast tumor samples that we analyzed revealed a high level of CLOCK protein compared to ERα-negative breast tumor samples (74% versus 46%), which suggested that the transcription of CLOCK in ERα-positive tumor may be upregulated." (PMID 24789043, 2014). "CLOCK expression levels are higher in more aggressive ERα-positive compared to ERα-negative breast tumours and estrogen promotes the binding of ERα to estrogen-response elements in the CLOCK promoter." (PMID 31014368, 2019). "In order to examine the relationship between CLOCK and ERα in breast tumor, we compared the protein levels of CLOCK and ERα in ERα-positive breast tumor samples with those of ERα-negative breast tumor samples." (PMID 24789043, 2014). "However, the role of CLOCK in breast tumor has not been elucidated." (PMID 24789043, 2014).
myocardial infarction (7 papers, 2008 to 2025). Gross necrosis of the myocardium, as a result of interruption of the blood supply to the area, as in coronary thrombosis. "Of note is a study by Skrlec and their colleague that explored the possible association between single nucleotide polymorphisms in three circadian rhythm genes (ARNTL, CLOCK, and PER2) and myocardial infarction inT2D." (PMID 36829576, 2023). "This study showed that genetic variation of the CLOCK gene was a biological sex difference in myocardial infarction patients." (PMID 34066863, 2021). "This study aimed to examine the potential difference of single nucleotide polymorphisms (SNPs) of the circadian rhythm genes ARNTL, CLOCK, CRY2 and PER2 in women and men with myocardial infarction." (PMID 34066863, 2021). "The present study found evidence of the difference between women and men in the recessive genotype model of the rs11932595 in the CLOCK gene in the sample of 200 patients with myocardial infarction." (PMID 34066863, 2021). "Nevertheless, patients carrying the CLOCK rs11932595 GG genotype were 2.66 times likely to have myocardial infarction." (PMID 34066863, 2021). "The aim of this study was to explore a possibility of association of the geneticvariability of the ARNTL, CLOCK, CRY2 andPER2 genes with myocardial infarction in humans." (PMID 29767668, 2018). "According to the study’s current results, the CLOCK gene’s genetic variability might affect myocardial infarction concerning biological sex." (PMID 34066863, 2021). "In non-T2D, the CLOCK SNP was no associated neither with stroke (HR: 1.59; 95 % CI 0.83–3–08; P = 0.165 nor with myocardial infarction (HR: 0.95; 95 % CI 0.48–1.89; P = 0.906)." (PMID 26739996, 2016). "On analysing specific causes of CVD, we obtained a significant interaction between the CLOCK-rs4580704 SNP and T2D status on stroke incidence (P for interaction: 0.018 in the dominant model 2), suggesting more specific effects for this outcome than for myocardial infarction." (PMID 26739996, 2016). "The genetic variability in the ARNTL, CLOCK, CRY2 and PER2 genes in this study showed that variations in the circadian genes differ between women and men with myocardial infarction." (PMID 34066863, 2021). "The present study was aimed at searching for a potential correlation between the SNPs of the CLOCK, ARNTL, and PER2 genes in patients with myocardial infarction." (PMID 32050674, 2020). "The downregulation of the biological clock gene BMAL1/CLOCK leads to circadian rhythm disruption and significant elevation of the pro-inflammatory cytokines CCL2, Interleukin-1 Beta( IL-1β), and IL-6 at the site of myocardial infarction in mice fed a high-fat diet, triggering cardiac inflammation." (PMID 40429770, 2025).
prostate carcinoma (7 papers, 2019 to 2026). A carcinoma that arises from epithelial cells of the prostate gland. "Other key CCCGs, including BMAL1, CLOCK, PER1/2/3, and RORα, are also shown to be associated with an increased risk of prostate cancer." (PMID 40948103, 2026). "Although a limited number of epidemiologic studies have been realized, several circadian genes have been implicated in prostate cancer regulation: ARNTL, CLOCK, CRY1-2, CSNK1e, MTNR1A and MTNR1B, NPAS2, NR1D1, PER1-3, RORA, RORB, and TIMELESS." (PMID 30873119, 2019). "The HPA database suggested that C18orf25, DYNC1LI2, SYNJ1, MAPK1, and ARID4B are highly expressed in normal tissues, and CLOCK, SETD2, ZNF654, XIAP, MIS18BP1, and MBTPS2 are highly expressed in prostate cancer tissues." (PMID 36249009, 2022). "Although the transcription factors of stemness genes have similar expressions, they have different contributions between normal and prostate cancer tissues; and particular transcription factors enhance the stemness of prostate cancer, such as PUM1, CLOCK, SP1, TCF12, and so on." (PMID 33985534, 2021).
Stroke (7 papers, 2016 to 2024). Sudden impairment of blood flow to a part of the brain due to occlusion or rupture of an artery to the brain. "Similar effects also existed in between rs10911021 and CAD in T2D as well as between CLOCK polymorphism and stroke in T2D patients." (PMID 30227878, 2018). "It is interesting to note that the association of the CLOCK-rs4580704 SNPs with stroke was only present in T2D subjects." (PMID 26739996, 2016). "Thus, only in T2D subjects was CLOCK-rs4580704 SNP associated with stroke risk, G-carriers having decreased risk (HR: 0.61; 95 % CI 0.40–0.94; P = 0.024 versus CC) in the multivariable-adjusted model." (PMID 26739996, 2016). "Finally, we tested the modulation by the dietary intervention of the association between the CLOCK-rs4580704 SNP and stroke in T2D subjects." (PMID 26739996, 2016). "These circadian variations may be more important in T2D patients and their dysregulation contributing to a higher CVD (mainly stroke) incidence in more susceptible individuals such as CLOCK-rs4580704 CC homozygous subjects (for whom our results suggest a lower flexibility)." (PMID 26739996, 2016). "Moreover, we detected a statistically significant interaction (P = 0.018) between CLOCK-rs4580704 SNP and T2D status on stroke." (PMID 26739996, 2016). "According to our results, we suggest circadian alterations due to functional genetic variants in core clock genes such as CLOCK as another factor that may contribute to this heterogeneity and higher risk of CVD (mainly, stroke) in those subjects." (PMID 26739996, 2016).
melanoma (6 papers, 2018 to 2025). A malignant, usually aggressive tumor composed of atypical, neoplastic melanocytes. "In melanoma, mRNA levels and nuclear immunopositivity for CLOCK, CRY1, and PER1 are reduced compared to adjacent non-tumorous skin and present a significant association with clinicopathological features such as Breslow thickness." (PMID 29946530, 2018). "Studies have demonstrated that CLOCK and BMAL1 affect cell proliferation by regulating the expression of Wee1, a kinase that inhibits cell cycle progression from G2 to M phase, suggesting a mechanism where disruptions in circadian rhythms could promote uncontrolled cell growth typical of melanoma." (PMID 40191195, 2025).